TLR2 (toll like receptor 2)
Diseases named in the same sentence as TLR2 in open-access papers (continued):
Sharing a sentence is not in itself a finding about the gene and the disease.
arteritis (2 papers, 2012). An inflammatory process affecting an artery. "L. casei cell wall extract (LCWE) develops arteritis in mice through Toll-like receptor-2 signaling." (PMID 22645447, 2012). "Recent studies suggesting signaling via Toll-like receptors (TLRs) in knockout mice indicate that TLR-2 signaling may play a role in LCWE-induced mouse arteritis." (PMID 22645447, 2012). "In addition, the LCWE-induced arteritis mouse model is feasible for studying the immunopathogenesis of coronary arteritis in human KD and for determining methods for the prevention of coronary arteritis in human KD by blocking TLR2-mediated immune activation on CD14+ monocytes." (PMID 22737215, 2012). "Since the importance of TLR2 in LCWE-mediated arteritis, the aim of our study was to assess the involvement of TLR2 on CD14+ monocytes in both human KD and LCWE-induced arteritis mice, and to further validate the translational application of this mouse model for investigating human KD." (PMID 22737215, 2012). "Taken together, TLR2 augmentation on monocytes may serve an inflammatory marker in both human KD patients and the LCWE-induced arteritis mouse model, and TLR2 may play a crucial role in the immunopathogenesis of human KD as in the LCWE-induced arteritis mouse model." (PMID 22737215, 2012).
astrocytoma (2 papers, 2018 to 2023). "This study aims to analyze the expression levels of plasmatic cell membrane TLRs (TLR1, TLR2, TLR4, TLR5, and TLR6) in human astrocytomas the most prevalent tumors of CNS different grades (II-IV)." (PMID 29912993, 2018). "TLR1, TLR2, TLR4, TLR5, and TLR6 are involved in a diversity of cellular responses, ranging from cell proliferation to cell death, and as such they are the targets of the current study in astrocytomas." (PMID 29912993, 2018). "In this regard, experimental evidence on the increased cell surface expression of TLR1, TLR2, TLR4, TLR5, and TLR6 in astrocytoma samples compared to non-neoplastic brain tissues clearly revealed the involvement of these TLRs in the progression of astrocytoma." (PMID 37822929, 2023). "In summary, increased cell membrane TLR1, TLR2, TLR4, TLR5, and TLR6 expressions were demonstrated in astrocytomas compared to non-neoplastic brain tissue, mostly in GBM group, and particularly in the mesenchymal subtype." (PMID 29912993, 2018). "In the present study, higher expression levels of TLR1, TLR2, TLR4, TLR5, and TLR6 were demonstrated in human diffusely infiltrating astrocytomas (grades II to IV) in comparison to non-neoplastic brain tissue." (PMID 29912993, 2018).
atopic asthma (2 papers, 2017 to 2023). An asthma that is characterized by symptoms that are triggered by an allergic reaction caused by inhaled allergens such as dust mite allergen, pet dander, pollen and mold. "In a large German study, a protective effect of genetic variants on atopic asthma was identified in the TLR2-associated heterodimer network consisting of TLR1, TLR6, and TLR1012." (PMID 28592890, 2017).
autoimmune myocarditis (2 papers, 2020 to 2022). Autoimmune myocarditis is an autoimmune disease that affects the heart. "Unlike autoimmune myocarditis, myasthenia gravis (MG) and its models require activation of TLR3 and TLR9, but not TLR2 and no NOD or NLR involvement has been reported for either patients or in animal models (although this may be because no one has yet looked for it)." (PMID 32629865, 2020).
autoimmune uveitis (2 papers, 2012 to 2013). An autoimmune form of uveitis (disease). "Thus, our data suggest that exogenous or endogenous molecules acting on both TLR2 and NOD2 on RACs might have an enhancing effect on susceptibility to autoimmune uveitis." (PMID 22808176, 2012). "Our previous studies showed that signaling of TLR2, TLR3, TLR4, and TLR9 is highly redundant in the adjuvant effect needed to induce experimental autoimmune uveitis (EAU)." (PMID 23207548, 2013).
B cell NHL (2 papers, 2016 to 2023). "A phase-1 single centric ENABLE clinical trial (NCT04049513) has been initiated using third-generation CD19 CAR (WZTL-002) incorporating the intracellular signaling domains of CD28 and Toll-like receptor 2 (TLR2) to identify a safety dose of R/R B cell NHL patients including MCL." (PMID 37626420, 2023).
B-cell acute lymphoblastic leukemia (2 papers, 2022 to 2023). A neoplasm of lymphoblasts committed to the B-cell lineage, typically composed of small to medium-sized blast cells. "CAR T cells also show an increased anti-tumor action against refractory or relapsed B cell acute lymphoblastic leukemia upon co-stimulation with TLR2 signaling by introducing the TIR domain of TLR2 into the CAR construct." (PMID 35309296, 2022).
bladder tumor (2 papers, 2021 to 2022). "BCG can stimulate TLR2/4 in bladder tumor cells to decrease cell proliferation and up-regulate apoptosis." (PMID 34141706, 2021). "Furthermore, the mechanism of monoclonal polysaccharide was investigated, and it was found that the TLR2/NF-κB/NLRP3 pathway promoted the polarization of TAM cells toward M1 and secreted pro-inflammatory factors to improve the bladder tumor microenvironment." (PMID 35603205, 2022).
Bovine mastitis (2 papers, 2018 to 2020). INFLAMMATION of the UDDER in cows. "In summary, these results suggest that SPB ameliorates the inflammatory response induced by S. aureus LTA via suppressing the TLR2/NF-κB/NLRP3 signaling pathway, which indicates that SPB may be a potential agent for the treatment of bovine mastitis." (PMID 30469547, 2018).
brain hemorrhage (2 papers, 2022 to 2023). "Increased expression of TLR2 and TLR4 receptors is linked to functional deficits within 3 months of a brain hemorrhage." (PMID 37168122, 2023). "It was found that the levels of IL-1β, IL-6, and TNF were significantly lower in TLR2 and TLR4 knockout mice after brain hemorrhage than in wild-type mice, thus supporting the link between TLR2 and TLR4 activation and M1 microglia." (PMID 36296682, 2022). "In addition, TLR2-TLR4 heterodimers trigger inflammatory responses, suggesting a role for TLR2 in brain hemorrhage similar to that of TLR4." (PMID 36296682, 2022). "It was found that neutrophils express TLR2 and Toll-like receptor 4 (TLR4), and brain hemorrhage is not only dependent on TLR2 receptors but also requires TLR4 receptors." (PMID 37168122, 2023).
brain tumor (2 papers, 2012 to 2017). "In contrast, the activation of TLR2 by HMGB1 during brain tumour therapy was reported to contribute to anti-tumour immunity via activation of dendritic cells." (PMID 28300057, 2017).
carditis (2 papers, 2009 to 2016). "Strikingly, inuPAR knock-out mice partially backcrossed to a B. burgdorferisusceptible C3H/HeN background, higher B. burgdorferi numberswere associated with more severe carditis and increased local TLR2 andIL-1β mRNA expression." (PMID 19461880, 2009). "Thus, T cells are increased in the inflammatory infiltrates in Lyme arthritis and carditis in TLR2−/− mice." (PMID 27857714, 2016). "Depletion of CD8+ T cells, however, lowered carditis severity in both the WT and TLR2−/− mice, indicating a role for CD8+ T cells in carditis severity." (PMID 27857714, 2016).
Chlamydia pneumonia (2 papers, 2014 to 2017). "Foam cell formation is implicated to be dependent on TLR2 activation as suggested in a TLR2-deficient mouse model infected with Chlamydia pneumonia." (PMID 25090652, 2014).
chronic gastritis (2 papers, 2015 to 2022). Inflammation of the stomach that is chronic in nature. "In this study we investigated for the first time the occurrence of alterations in the TLR2 and TLR4 mRNA and protein expression in H. pylori-infected patients with chronic gastritis, before and after successful bacteria eradication treatment." (PMID 25873761, 2015). "Thus, we evaluated the effect of eradication therapy on TLR2 and TLR4 mRNA and protein expression in H. pylori-infected chronic gastritis patients (CG-Hp+) and 3 months after treatment." (PMID 25873761, 2015).
chronic gingivitis (2 papers, 2020 to 2022). Chronic painless inflammation of the gums. "More commonly, TLR2 agonists are produced by multiple systemic infectious agents affecting patients, including chronic gingivitis, skin pathogens, and gut microbiome." (PMID 32059733, 2020).
chronic GVHD (2 papers, 2011 to 2020). "Here we report studies of a patient with chronic GvHD (cGvHD) carrying persistent CD4+ T cell clonal expansion harboring somatic mTOR, NFKB2, and TLR2 mutations." (PMID 32382059, 2020). "Furthermore, investigators have reported that TLR2 stimulation can induce Th2 immunity, which is the prominent immunity of chronic GVHD, whereas TLR9 stimulation promotes Th1 immune responses, the characterized immunity of acute GVHD." (PMID 22025895, 2011).
chronic lung disease (2 papers, 2010 to 2025). According to the definitions of the American and British Thoracic Societies, including pulmonary functional tests, X-rays, and CT scans for items such as fibrosis, bronchiectasis, bullae, emphysema, nodular or lymphomatous abnormalities. "Our data for the first time suggest that airway epithelial TLR2 signaling is pivotal in mycoplasma-induced SPLUNC1 production, thus improving our understanding of the aberrant SPLUNC1 expression in airways of patients suffering from chronic lung diseases with bacterial infections." (PMID 21054862, 2010).
Chronic pain (2 papers, 2009 to 2013). Persistent pain, usually defined as pain that has lasted longer than 3 to 6 months. "Chronic pain patients have increased peripheral blood mononuclear cell Interkeukin-1β production following TLR2 and TLR4 simulation." (PMID 24204973, 2013). "Interestingly, we have recently demonstrated that in chronic pain patients, peripheral blood mononuclear cells (PBMCs) also have increased TLR2 and TLR4 responsiveness compared with pain-free participants, suggesting that this could be a potential pain biomarker." (PMID 24204973, 2013).
coagulation disorders (2 papers, 2007 to 2022). "Since TF expression is under the control of transcription factors such as nuclear factor κB (NFκB), which is also activated by TLR2, it is tempting to speculate that tlr2 polymorphisms may influence the severity of coagulation disorders in invasive streptococcal infections." (PMID 17660410, 2007).
congenital toxoplasmosis (2 papers, 2013 to 2021). Toxoplasma infection that is present from birth. "In this study, we investigated the role of TLR2 in congenital toxoplasmosis using TLR2-deficient (TLR2−/−) mice." (PMID 34675905, 2021). "Therefore, the regulation of TLR2 signaling may be a potential target in controlling congenital toxoplasmosis." (PMID 34675905, 2021). "In this article, we present reasons for the research of the plausible role of SNPs residing in TLR2, TLR4, and TLR9 genes in congenital toxoplasmosis development." (PMID 23161283, 2013). "We suppose that genetic modifications, especially of TLR2, TLR4, and TLR9, might play a plausible role in congenital toxoplasmosis development." (PMID 23161283, 2013).
contact dermatitis (2 papers, 2017 to 2025). An inflammatory skin condition caused by direct contact between the skin and either an irritating substance or an allergen. "In the CHS model the loss of TLR2 and TLR4 leads to resistance against contact dermatitis, i.e. either the oxidative stress and the in flammasome pathways alone are not sufficient to permit contact dermatitis or these pathways are not efficiently activated without these TLR." (PMID 30402600, 2017). "Studies in the mouse model of contact dermatitis, the contact hypersensitivity (CHS) model, showed that the simultaneous absence of TLR2 and TLR4 leads to resistance against potent contact allergens like TNCB and oxazolone." (PMID 30402600, 2017).
corneal diseases (2 papers, 2022 to 2025). "Keratoconus (KC) is a corneal disorder whose etiology shares a close relationship with Lactoferrin (LTF) dysregulation and Toll-like Receptors 2 (TLR2) overexpression." (PMID 36293206, 2022).
Cryptococcal meningitis (2 papers, 2016 to 2021). Meningeal inflammation produced by cryptococcus neoformans, an encapsulated yeast that tends to infect individuals with acquired immunodeficiency syndrome and other immunocompromised states. "Peripheral blood mononuclear cells (PBMCs) isolated from patients with cryptococcal meningitis exhibited a significant reduction in TLR2 expression compared to healthy control PBMCs and blocking TLR2 on PBMCs led to a reduction in IL-12p70 and IFN-γ when stimulated with Cryptococcus." (PMID 26903984, 2016).
dilated cardiomyopathy (2 papers, 2023 to 2025). Cardiomyopathy which is characterized by dilation and contractile dysfunction of the left and right ventricles. "A significantly lower LVPWd in AAV9-TLR2-injected mice than in AAV9-control-injected mice repressed dilated cardiomyopathy; moreover, the cardiac-specific overexpression of TLR2 aggravated TAC-induced cardiac dysfunction." (PMID 41552821, 2025). "TLR2 and TLR4 have been shown to play a role in the pathogenesis of dilated cardiomyopathy." (PMID 38140398, 2023).
endometrial cancer (2 papers, 2010 to 2019). Primary or metastatic malignant neoplasm involving the endometrium (mucous membrane that lines the endometrial cavity). "Ten polymorphisms were genotyped in 191 endometrial cancer cases and 291 controls using real-time PCR: NOD1 (rs2075822, rs2907749, rs2907748), NOD2 (rs5743260, rs2066844, rs2066845), TLR2 (rs5743708), TLR4 (rs4986790) and TLR9 (rs5743836, rs187084)." (PMID 20646321, 2010). "For these reasons, we sought to determine if genetic variation in a number of TLRs and NOD genes (TLR2, TLR4, TLR9, NOD1 and NOD2) were associated with risk of developing endometrial cancer." (PMID 20646321, 2010). "Kaplan-Meier survival analysis and T-tests were used to evaluate the influence of the NOD1, NOD2, TLR2, TLR4 and TLR9 polymorphisms on the age of diagnosis of endometrial cancer." (PMID 20646321, 2010). "With respect to the TLRs, TLR2, TLR4 and TLR9 are highly polymorphic and represent interesting targets to elucidate their role in endometrial cancer development." (PMID 20646321, 2010).
enteropathy (2 papers, 2020 to 2025). "Consistent with our previous results, a rat model of diclofenac-induced enteropathy revealed that S. boulardii CNCM I-745 prevented TLR2/4, MYD88, and NF-κB p65 overexpression, thereby decreasing proinflammatory cytokines, such as IL-1β." (PMID 40872558, 2025). "Recently, it has been reported that the combination of lactoferrin with Bifidobacterium longum protects against diclofenac induced-enteropathy in rats partially by modulating the TLR-2/-4/NF-κB pathways." (PMID 32848762, 2020).
epithelial dysplasia (2 papers, 2011 to 2018). "Normal or hyperplastic epithelium showed TLR2 and A2a staining in the basal and parabasal cells (panel “Hyperplasia”), while TLR2- and A2a-positive squamous cells in epithelial dysplasia (ED) and in OSCC were present throughout the lesions." (PMID 29467931, 2018). "We show that in vivo, keratinocytes in epithelial dysplasia and in OSCC expressed both TLR2 and A2a." (PMID 29467931, 2018). "In order to verify the relevance of TLR2 and A2a to SCC in vivo, we evaluated the expression of these receptors in 17 archival specimens of human epithelial dysplasia/OSCC." (PMID 29467931, 2018).
essential thrombocythemia (2 papers, 2021 to 2025). A chronic myeloproliferative neoplasm that involves primarily the megakaryocytic lineage. "Moreover, platelet TLR2 and TLR4 are important for the formation of platelet-neutrophil aggregates in patients with essential thrombocythemia." (PMID 34527000, 2021).
extrapulmonary tuberculosis (2 papers, 2010 to 2023). A tuberculosis that occurs at body sites other than the lung. "The results of this study suggest that an evaluation of the underlying mechanism(s) of the genetic variants in IL-1β +3953, VDR Fok1 A/G, and the TLR2 microsatellite--and their role in the pathogenesis of extrapulmonary tuberculosis--is warranted." (PMID 20196868, 2010). "TLR-2 and TLR-4 serum scores were higher in patients with extrapulmonary tuberculosis, in addition to serum TLR-2, TLR-4 was higher in those with BCG scars than in those without BCG, and statistical analysis results showed a significant difference." (PMID 38129893, 2023). "In this pilot study among extrapulmonary tuberculosis patients with well-characterized immune defects, genetic variants in IL-1β, VDR Fok1, and TLR2 were associated with an increased risk of extrapulmonary disease." (PMID 20196868, 2010). "The TLR2 microsatellite predicted extrapulmonary tuberculosis in black patients with 76% accuracy." (PMID 20196868, 2010).
gastric ulcer (2 papers, 2013 to 2025). An ulcerated lesion in the mucosal surface of the stomach. "Numerous studies demonstrate that the TLR-2/MyD88 signaling pathway is critical for the formation and progression of gastric ulcers." (PMID 40563542, 2025). "TLR4 and RAGE deficiency promoted gastric ulcer formation and prevented the increase in TNFα mRNA expression after ulceration, whereas TLR2 deficiency affected neither the ulcer index nor the expression of TNFα mRNA." (PMID 24244627, 2013).
Gliosis (2 papers, 2019 to 2022). Gliosis is the focal proliferation of glial cells in the central nervous system. "Also, in patients with metabolic disorder, the accumulation of a specific sphingosine can trigger gliosis and leukodystrophy via TLR2-mediated activation of innate immunity." (PMID 31766565, 2019). "Interestingly, the inhibition of either of the two pathways separately showed no beneficial effect, whereas the activation of either Tlr2 or Cxcr3 in the nostril paradigm was sufficient to induce gliosis." (PMID 35159329, 2022).
Hashimoto’s disease (2 papers, 2019 to 2023). "Due to the limited number of patients enrolled in the study, it is important to conduct further interdisciplinary studies to clarify the exact role of TLR2 in the immunopathogenesis of Hashimoto’s disease." (PMID 36982416, 2023). "They observed, among others things, a markedly increased TLR-2 expression in the peripheral blood of patients with newly diagnosed GD or with Hashimoto thyroiditis compared to the control group." (PMID 31554206, 2019). "This is due to the increased percentages of both dendritic cells and monocytes expressing TLR2 on their surface in patients with Hashimoto’s disease in relation to the control group, as well as a more than six-fold increase in the concentration of sTLR2 in the plasma of the patients." (PMID 36982416, 2023). "The results of our research presented in this publication suggest that TLR2 may significantly influence the dysregulation of the functioning of the immune system and thus the development and progression of Hashimoto’s disease." (PMID 36982416, 2023).
herpesvirus infection (2 papers, 2020 to 2022). "The other significant pathways are Kaposi’s sarcoma-associated herpesvirus infection (steered by ZFP36 and CXCL2), PI3K-Akt signaling pathway and the proteoglycans in cancer pathways (steered by IGF2 and TLR2)." (PMID 35277538, 2022). "In response to herpesvirus infection, TLR2 plays a role in inducing interferon γ in neurons and cytokines in peritoneal macrophages, as well as controlling viral load in the CNS." (PMID 33027661, 2020). "How the modulation of TLR2 by pUL56 and other viral proteins differentially affects the pathogenesis of herpesvirus infections awaits further study." (PMID 33027661, 2020).